TM6SF2 (transmembrane 6 superfamily member 2)
Diseases named in the same sentence as TM6SF2 in open-access papers (continued):
Sharing a sentence is not in itself a finding about the gene and the disease.
mitochondrial disease (1 paper, 2025). "Since MASLD occurs as a mitochondrial disease and the PNPLA3, MBOAT7 and TM6SF2 loss-of-function mutations seem to achieve a role in organelles’ dysfunction, in this study, we firstly investigated the impact of gene deletion on mitochondrial dynamism and integrity in KO HepG2 cells." (PMID 40563253, 2025).
TM6SF2 also shares sentences with these, for which no sentence is quoted: Hypertension (5 papers); cancer (3); coronary heart disease (3); metabolic disease (3); alcohol (2); all (2); Ascites (1); asthma (1); astrocytoma (1); autoimmune conditions (1); Cholestatic liver disease (1); chronic kidney disease (1); Hypocholesterolemia (1); inflammation (1); lipid metabolism disorders (1); periodontitis (1); portal hypertension (1); primary sclerosing cholangitis (1); rheumatoid arthritis (1); Sjogren syndrome (1).